DTX3L (deltex E3 ubiquitin ligase 3L)
Diseases named in the same sentence as DTX3L in open-access papers (continued):
Sharing a sentence is not in itself a finding about the gene and the disease.
glioma (4 papers, 2021 to 2026). A benign or malignant brain and spinal cord tumor that arises from glial cells (astrocytes, oligodendrocytes, ependymal cells). "DTX3L is also highly expressed in gliomas, and its expression level has been shown to correlate with the degree of malignancy and overall prognosis." (PMID 36614304, 2023). "DTX3L is also highly expressed in gliomas, and its expression level correlates with the degree of malignancy and the overall prognosis." (PMID 34513839, 2021).
triple-negative breast carcinoma (4 papers, 2021 to 2025). An invasive breast carcinoma which is negative for expression of estrogen receptor (ER), progesterone receptor (PR), and human epidermal growth factor receptor 2 (HER2). "DTX3L, an E3-ubiquitin ligase, is required for maintaining LIPG protein levels by inhibiting proteasome-mediated LIPG degradation, and DTX3L-LIPG-ISG15 signaling is essential for malignancies of triple-negative breast cancer cells (TNBCs)." (PMID 35159348, 2022). "Endothelial Lipase (LIPG): ISGylation mediated by Deltex-3-like E3 ubiquitin ligase (DTX3L) prevents LIPG ubiquitin-dependent degradation, promoting tumourigenicity and metastasis in triple-negative breast cancer (TNBC)." (PMID 40103488, 2025).
lymphoma (3 papers, 2015 to 2023). A malignant (clonal) proliferation of B- lymphocytes or T- lymphocytes which involves the lymph nodes, bone marrow and/or extranodal sites. "Since DTX3L monoubiquitylates Histone H4 and selectively modulates the DNA damage response, lymphomas with increased expression level of DTX3L are resistant to DNA-damaging chemotherapeutic agents." (PMID 26033450, 2015).
myeloma (3 papers, 2018 to 2024). "Meanwhile, inhibition of DTX3L expression has been shown to enhance the sensitivity to chemotherapy and increase the expression of caspase-3 and PARP1 in multiple myeloma cell lines, thus promoting apoptosis." (PMID 34513839, 2021). "The expression of DTX3L is regulated by FAK and gradually increases during proliferation of myeloma cells, which results in cell cycle arrest at the G1 phase and promotes the adhesion of myeloma cells to fibronectin or bone marrow stromal cells." (PMID 34513839, 2021). "DTX3L was found to be regulated by focal adhesion kinase and represents another pathway through which CAM-DR is induced in myeloma cells." (PMID 29765356, 2018).
Cerebral arteriovenous malformation (2 papers, 2022 to 2023). "METTL3 plays a similar role in cerebral arteriovenous malformation, and deletion of METTL3 in ECs significantly affects angiogenesis by reducing heterodimeric Notch E3 ubiquitin ligase formed by DTX1 and DTX3L." (PMID 35001873, 2022). "DTX3L has also been found up-regulated by METTL3, an RNA N6-methyladenosine (m6A) transferase In particular, downregulation of the METTL3-DTX1/DTX3L dimer axis, upregulates NOTCH signaling, impairs angiogenesis in vitro, and correlates with cerebral arteriovenous malformations." (PMID 37443713, 2023).
head and neck squamous cell carcinoma (2 papers, 2024 to 2025). A squamous cell carcinoma that arises from any of the following anatomic sites: lip and oral cavity, nasal cavity, paranasal sinuses, pharynx, larynx, and salivary glands. "PARP9, its binding partner DTX3L and PARP14 protein levels are significantly correlated in head and neck squamous cell carcinoma (HNSCC) and other tumour types though a mechanism where PARP9/DTX3L regulates PARP14 post-transcriptionally." (PMID 38182103, 2024). "We have explored further the molecular requirements of PARP9/DTX3L and PARP14 mediated survival using head and neck squamous cell carcinoma (HNSCC) and HeLa cell lines, which have increased PARP9/DTX3L and PARP14 expression." (PMID 38182103, 2024).
HIV-1 infection (2 papers, 2017 to 2020). The type species of lentivirus and the etiologic agent of acquired immunodeficiency syndrome (AIDS). "The identified three genes play all a role in the interferon-mediated antiviral response: PARP9 is increased in vitro models of HIV-1 infection and, together with DTX3L, can target histone H2BJ and increase the expression of interferon stimulated genes (ISGs)." (PMID 32760119, 2020).
metastatic prostate carcinoma (2 papers, 2014 to 2015). A carcinoma that arises from the prostate gland and has spread to other anatomic sites. "In metastatic prostate cancer cell lines, survival and chemoresistance in response to IFNγ are mediated by ARTD9 with its interaction partner DTX3L/BBAP in a STAT1-dependent way." (PMID 26426055, 2015).
Cachexia (1 paper, 2024). Severe weight loss, wasting of muscle, loss of appetite, and general debility related to a chronic disease. "Recently, several studies have shown that the expression of DTX3L is associated with inflammatory diseases.S5 Our previous research showed that LC alleviates the decrease in skeletal muscle mass and inflammation induced by cachexia in mice and activates the AKT (protein kinase B) pathway." (PMID 39091264, 2024). "To determine the role of DTX3L in this model, we checked the expression of DTX3L in mice with cachexia." (PMID 39091264, 2024). "DTX3L was expressed at an abnormal level in the cachexia model, while LC restored the protein level of DTX3L to the normal (control) level." (PMID 39091264, 2024).
cervical cancer (1 paper, 2023). A primary or metastatic malignant neoplasm involving the cervix. "Therefore, our results suggested that DTX3L is involved in the development of cervical cancer and may become a new strategy for cervical cancer treatment." (PMID 36614304, 2023).
COVID-19 (1 paper, 2024). A disease caused by infection with severe acute respiratory syndrome coronavirus 2. "Both genes were also coenriched in the Notch pathway, TLE3, and NCSTN; nonetheless, CTBP1 significantly differed in the COVID-19 comparison group, whereas DTX3L was more significant in the PQ comparison group." (PMID 39301288, 2024).
gastric cancer (1 paper, 2026). A primary or metastatic malignant neoplasm involving the stomach. "Here, we identify Deltex E3 ubiquitin ligase 3L (DTX3L) as a previously unrecognized tumor suppressor in gastric cancer." (PMID 41972409, 2026). "DTX3L expression is markedly reduced in metastatic and mesenchymal-type gastric cancers and positively correlates with favorable patient prognosis." (PMID 41972409, 2026). "Functional analyses in cell lines, organoids and animal models demonstrate that DTX3L depletion promotes gastric cancer cell migration, invasion, stem-like properties and metastasis, whereas its overexpression exhibits opposite effects." (PMID 41972409, 2026).
glioblastoma (1 paper, 2024). The most malignant astrocytic tumor (WHO grade IV). "We compared protein expression of PARP14 and its binding partner, DTX3L, proteins in a panel of different cell lines, (HNSCC; Glioblastoma GBM; Prostate Adenocarcinoma PRAD; and Pancreatic Adenocarcinoma PAAC)." (PMID 38182103, 2024).
liver cancer (1 paper, 2023). An epithelial or non-epithelial malignant neoplasm that arises from the liver. "Besides, our analysis of The Cancer Genome Atlas database revealed heightened expression of DTX3L in liver cancer tissues compared to normal tissues." (PMID 38042777, 2023).
oral cancers (1 paper, 2019).
pancreatic cancer (1 paper, 2018). "We measured the expression of key members of the Notch Signaling Pathway (NUMB, DTX4, DTX3L, PSEN1, APH1A, ADAM17 and EP300) in the MiaPaCa-2-miR-148a by qRT-PCR, and compared it with the basal levels of the control pancreatic cancer cell line MiaPaCa-2, expressing very low levels of miR-148a." (PMID 29464088, 2018).
prostate tumors (1 paper, 2014). "Thus, further studies need to be carried out in order to determine whether simultaneous ectopic co-overexpression of ARTD9 together with wild type or enzymatic mutant forms of DTX3L and/or ARTD8 in xenograft prostate tumors confer docetaxel resistance and/or enhance metastasis in vivo." (PMID 24886089, 2014).
skin infection (1 paper, 2019). An inflammatory process affecting the skin, caused by bacteria, viruses, parasites, or fungi. "Together with this evidence, we proposed the potential role of DTX3L in diabetic keratinocytes, which may be related to the impaired wound healing and susceptibility to skin infection of patients with T2D." (PMID 30634634, 2019).
skin melanoma (1 paper, 2019). "Research on DTX3L has mainly focused on its role in tumor cell growth and adhesion, including skin melanoma." (PMID 30634634, 2019).
tumor (18 papers, 2014 to 2026). "Further studies showed that the tumor-promoting effect of DTX3L was associated with the PI3K/AKT/mTOR signaling pathway." (PMID 36614304, 2023). "The present study further suggests that the combined targeted inhibition of STAT1, ARTD8, ARTD9 and/or DTX3L could increase the efficacy of chemotherapy or radiation treatment in prostate and other high-risk tumor types with an increased STAT1 signaling." (PMID 24886089, 2014). "Taken together, our study suggests that the combined targeted inhibition of STAT1, ARTD8, ARTD9 and/or DTX3L could increase the efficacy of chemotherapy or radiation treatment in prostate and other high-risk tumor types with an increased STAT1- and STAT3-signaling." (PMID 24886089, 2014). "This implies that targeting the DTX3L-cGAS axis holds the potential to enhance the prognosis of patients with SKCM by augmenting anti-tumor immunity." (PMID 41409301, 2025). "In summary, we have provided insight into the structure and interactions between two macro-PARP family members and DTX3L that have several pro-tumour functions." (PMID 38182103, 2024). "The DTX3L gene, also known as BBAP (B-lymphoma and BAL-associated protein), plays regulatory functions on DNA damage signaling, tumor cell growth, and IFN signaling and antiviral response." (PMID 38982354, 2024). "DTX3L shows an altered expression level during tumor progression in multiple carcinomas." (PMID 36614304, 2023). "In addition, the results of in vivo assays confirmed the tumor-promotive roles of DTX3L in CC development." (PMID 36614304, 2023). "Additionally, the TCGA cohort dataset showed that DTX3L expression was significantly higher in both CC tumor tissues and metastatic CC compared with that in normal cervical tissues." (PMID 36614304, 2023). "Our finding of DTX3L-dependent regulation of LIPG expression may have important implications to tumor-microenvironmental interactions occurring in TNBCs through secreted immune cytokines like IFNs." (PMID 29350614, 2018). "Therefore, a combined targeted inhibition of STAT1, PARP9, PARP14 and/or DTX3L could increase the efficacy of currently available treatment for prostate, DLBCL and other high-risk tumour types harbouring an increased STAT1 signalling." (PMID 39189367, 2024). "More recently, PARP14 protein levels were found to be increased in HNSC and other tumour types, along with elevated protein levels of its interactors PARP9 and DTX3L." (PMID 39189367, 2024). "For example, various carcinogenic factors, such as miR-383, deltex (DTX)-3-like E3 ubiquitin ligase (DTX3L) and poly (ADP-ribose) polymerase family member 9 (PAPR9), have been shown to promote tumour metastasis and invasion by targeting IRF-140,41." (PMID 31186404, 2019). "Depletion of several ubiquitinases and proteasome components (DTX3L, UBE2E1, RNF31, RNF115, USP2, USP42, PSMC3, and PSMD10) were also found to inhibit tumor cell migration." (PMID 31278301, 2019). "Our study demonstrates that DTX3L and ARTD9 cooperate as repressors of the tumor suppressor IRF1 in mPCa cells." (PMID 24886089, 2014). "Xenograft studies further demonstrated that similar to DTX3L knockdown, knockdown of either LIPG or ISG15 completely abolished the DTX3L overexpression-enhanced growth of MDA-MB-468 xenograft tumors and also significantly inhibited tumor development." (PMID 29350614, 2018). "DTX3L and ARTD9 act together as repressors of the tumor suppressor IRF1 in mPCa cells." (PMID 26654227, 2015). "Recent studies provided first evidence that ARTD9 and DTX3L might act in a (poly or) mono-ADP-ribosylation-dependent DNA damage response pathway and together with ARTD1 enhance tumor cell survival." (PMID 26654227, 2015). "Our initial aim was to explore the expression of pro-tumour ADP-ribosyltransferases PARP14 and PARP9/DTX3L particularly in HNSCC, which are characteristically resistant to treatment and PARP9/14 mediated survival might represent a mechanism for increased survival." (PMID 38182103, 2024).
tumor (continued). "IRF1 and DTX3L induction by ATRA is specific, since it is not observed with other anti-tumor agents, as exemplified by the results obtained in HCC-1599 cells." (PMID 32384653, 2020).
cancer (12 papers, 2015 to 2026). A tumor composed of atypical neoplastic, often pleomorphic cells that invade other tissues. "DTX3L, an emerging E3 ubiquitin ligase of the Deltex family, is closely associated with the development and progression of various malignant tumors." (PMID 41883974, 2026). "MMP-1 overexpression has been associated with metastasis in numerous cancers, and DTX3L has been reported to protect DNA from oxidative stress." (PMID 34073779, 2021). "However, the effects of LC on DTX3L, the role of DTX3L in fibrosis and their relationship with cancer cachexia‐associated SMF are currently unclear." (PMID 39091264, 2024). "From a clinical translation perspective, DTX3L, with its unique substrate selectivity, is becoming a promising cancer therapeutic target." (PMID 41883974, 2026). "This review systematically summarizes cutting-edge research findings on DTX3L across numerous malignant tumors and analyzes its regulatory mechanisms and functional manifestations in these cancers." (PMID 41883974, 2026). "The overexpression of the PARP9:DTX3L complex is observed in various cancers such as prostate and breast cancers, indicating its promoting role in the growth of cancer cells." (PMID 38000390, 2024). "This study aimed to characterise the interactions and structural requirements of the complex of PARP9/DTX3L and PARP14 which is implicated in survival of several cancer cell types." (PMID 38182103, 2024). "We also showed that LC regulates Runx2 ubiquitination through DTX3L, leading to a decrease in COL1A1 and alleviating SMF caused by cancer cachexia." (PMID 39091264, 2024). "•PARP9 and DTX3L regulate PARP14 protein levels therefore depleting PARP9, DTX3L or PARP14 mRNA results in loss of PARP14 protein and a reduction in cancer cell survival through a loss of proliferation and increase in apoptosis." (PMID 38182103, 2024). "The previous research on DTX3L has mainly focused on tumours, where it has been shown to be involved in cancer cell survival, proliferation, apoptosis, metastasis and DNA repair." (PMID 39091264, 2024). "In this study, we found that LC alleviates fibrosis through the DTX3L/Runx2/COL1A1 axis in our models of cancer cachexia." (PMID 39091264, 2024). "This study revealed a previously unrecognized link between Runx2 and DTX3L in SMF and demonstrated that l‐carnitine exerted a significant therapeutic impact on cancer cachexia‐associated SMF, potentially through the upregulation of DTX3L." (PMID 39091264, 2024). "TBK1 is aberrantly activated in various human cancers, however, and it would be interesting to determine if the TBK1-mediated phosphorylation of DTX3L is involved in driving cancer cell survival." (PMID 35204725, 2022). "Given that IFNs can induce DTX3L expression, IFNs may enhance LIPG expression in cancer cells through their stimulating effects on DTX3L expression." (PMID 29350614, 2018). "Since cancer cell survival was not dependent on PARP14 catalytic activity we postulate that PARP9/DTX3L regulates PARP14 expression and activity to promote proliferation and anti-apoptosis." (PMID 38182103, 2024). "Our work reveals DTX3L as a key regulator of TIRR function and DNA repair, suggesting that increased expression of DTX3L could be a target for PARP inhibitors in the treatment of cancer." (PMID 39632881, 2024).
adenocarcinoma (1 paper, 2016). A common cancer characterized by the presence of malignant glandular cells. "We however also observed one protein that was down-regulated in SCC while up-regulated in adenocarcinoma (VWA8) and vice versa 7 proteins showing the opposite behavior (FAK2, PMM2, K2C5, SMCA5, FAD1, DTX3L and CLU)." (PMID 26930711, 2016).
infection (1 paper, 2025). The state of being infected such as from the introduction of a foreign agent such as serum, vaccine, antigenic substance or organism. "We found that, in addition to a broad induction of ISGs (for example, DTX3L, OAS3, RTP4, IRF7, MX2, IFIT3, IFIH1), only IFNB1 and, more robustly, IFNL1-like and IFNL3-like were induced in virus-infected organoids at 1 and 3 days after infection compared to the uninfected controls." (PMID 40399606, 2025).
DTX3L also shares sentences with these, for which no sentence is quoted: hepatocellular carcinoma (2 papers); anemia (1); aortic stenosis (1); autoimmune disease (1); benign tumors (1); bladder cancer (1); fibrosarcoma (1); leukemia (1); metastatic melanoma (1); Moyamoya disease (1); multiple myeloma (1); nevus (1); non-small cell lung carcinoma (1); pancreatic adenocarcinoma (1); prostate adenocarcinoma (1); rheumatoid arthritis (1).